GSTT2B (glutathione S-transferase theta 2B)
Description:
Conjugation of reduced glutathione to a wide number of exogenous and endogenous hydrophobic electrophiles. Has a sulfatase activity.
Synonyms: GSTT2P
Tractability: Small molecule: it has a high-quality binding pocket. PROTAC: ubiquitination databases record sites on it.
Gene: Protein-coding gene on chromosome 22 (23,957,414 to 23,961,197, reverse strand). Ensembl gene ENSG00000133433.
Subcellular location: Cytoplasm, cytosol
Subcellular location (Human Protein Atlas): Cytosol; Nucleoplasm
Pathways (Reactome):
Metabolism: Glutathione conjugation
Gene Ontology:
Molecular function: glutathione transferase activity; protein binding
Biological process: glutathione metabolic process
Cellular component: cytosol; extracellular exosome; cytoplasm
Genetic constraint (gnomAD): Loss-of-function variants: 4 observed, 6.65 expected, observed/expected ratio (o/e) 0.6, 90% interval 0.29 to 1.36. That is too few expected variants to judge how well the gene tolerates losing a copy. Missense variants: 23 observed, 80.81 expected, observed/expected ratio (o/e) 0.28, 90% interval 0.2 to 0.4. Synonymous variants: 9 observed, 28.75 expected, observed/expected ratio (o/e) 0.31, 90% interval 0.19 to 0.55.
Homologues: Orthologues: macaque GSTT2B (90% identical), mouse Gstt2 (78% identical), rat Gstt2 (61% identical), zebrafish gstt2 (36% identical), Drosophila melanogaster GstT3 (30% identical), Drosophila melanogaster GstT1 (28% identical), Drosophila melanogaster GstE12 (27% identical), Drosophila melanogaster GstE2 (27% identical), Drosophila melanogaster GstE1 (26% identical), Drosophila melanogaster GstT2 (26% identical), Drosophila melanogaster GstE6 (25% identical), Drosophila melanogaster GstE3 (25% identical), and 33 more. Paralogues in human: GSTT2 (99% identical), GSTT4 (42% identical), EEF1G (27% identical), GDAP1 (25% identical), CLIC1 (21% identical), GDAP1L1 (21% identical), CLIC4 (21% identical), CLIC6 (21% identical), CLIC5 (20% identical), CLIC3 (20% identical), CLIC2 (19% identical), GSTZ1 (19% identical), and 2 more.
Diseases named in the same sentence as GSTT2B in open-access papers:
GSTT2B is named in the same sentence as 3 diseases in open-access papers, as found by Europe PMC text mining. Sharing a sentence is not in itself a finding about the gene and the disease. The quoted sentences say what the papers report.
bladder cancer (1 paper, 2024). "A panel of human bladder cancer and promonocytic cell lines was examined for GSTT2B deletion status." (PMID 39201633, 2024). "In this study, we evaluated the GSTT2B status of a panel of human bladder cancer and promonocytic cell lines." (PMID 39201633, 2024). "The impact of GSTT2B and GSTT1 deletions and selected GSTT2 promoter SNPs on the development of bladder cancer and the response of bladder cancer patients to BCG immunotherapy were determined." (PMID 39201633, 2024).
cancer (3 papers, 2009 to 2024). A tumor composed of atypical neoplastic, often pleomorphic cells that invade other tissues. "This is, to our knowledge, the largest investigation to date of the association of GST functional polymorphisms with cancer in African populations, and the first to assess the role of the GSTT2B deletion in cancer risk." (PMID 22216261, 2011). "This is the first report of the contribution of the GSTT2B deletion to cancer risk." (PMID 22216261, 2011). "Consistent with the results from cancer cell lines, GSTT2 expression was strong in a fibroblast homozygous for the non-deletion allele, was weaker but detectable when heterozygous, and was undetectable in cell lines homozygous for the GSTT2B deletion." (PMID 19424424, 2009).
tumour (1 paper, 2024). "Hence, GSTT2B status may not only impact immune function but could also affect tumour cell response to BCG treatment." (PMID 39201633, 2024).